IL6 (interleukin 6)
Diseases named in the same sentence as IL6 in open-access papers (continued):
Sharing a sentence is not in itself a finding about the gene and the disease.
atherosclerosis (continued). "Furthermore, this inflammation is a key pathological link between immune dysfunction and the vastly elevated cardiovascular risk in ESRD, as pro-inflammatory cytokines like IL-6 and TNF-α promote endothelial dysfunction, atherosclerosis, and vascular calcification." (PMID 41010736, 2025). "During recovery, however, the lower IL-6 concentrations may protect against atherosclerosis." (PMID 39957063, 2025). "Chronic HCV infection, for instance, is associated with an increased risk of atherosclerosis and coronary artery disease (CAD), likely mediated by persistent immune activation and elevated levels of proinflammatory cytokines like tumor necrosis factor-alpha (TNF-α) and interleukin-6 (IL-6)." (PMID 40787484, 2025). "Therefore, these alterations could lead to production of specific inflammatory cytokines, such as IL-1, IL-6, and TNF-a, and enhancement of inflammation, all known risk factors for the development of atherosclerosis and CAD." (PMID 40566026, 2025). "Elevated levels of inflammatory markers such as interleukin-6 (IL-6) and C-reactive protein (CRP) have been consistently observed in HIV-positive individuals and are strongly associated with endothelial dysfunction, accelerated atherosclerosis, and myocardial injury." (PMID 40787484, 2025). "Furthermore, interleukin (IL)-6 is a common pathological factor in RA and atherosclerosis." (PMID 39897309, 2025). "Additionally, bilirubin can inhibit inflammatory responses by suppressing the release of various inflammatory mediators (e.g., TNF-α, IL-6), thus reducing inflammation-induced damage to vascular endothelial cells and preventing atherosclerosis and other cardiovascular diseases." (PMID 39188917, 2024). "Furthermore, CRP and IL-6 are described to be elevated in atherosclerosis and therefore the higher levels of CRP and IL-6 in the RA risk group might partly be explained by the underlying atherosclerotic process." (PMID 39012360, 2024). "In an atherosclerosis mouse model, estrogen can reduce atherosclerotic plaque burden, decrease the upregulation of endothelial cell adhesion molecules induced by cytokines, and reduce interleukin-6 expression, thereby inhibiting inflammation and reducing CHD incidence." (PMID 39618953, 2024). "Overall, it appears that while the complete lifetime absence of IL-6 leads to vascular maladaptation and reduced atherosclerosis in animal models, increased circulating IL-6 levels in patients are associated with the development and severity of atherosclerotic disease." (PMID 38256155, 2024). "Pro-inflammatory cytokines such as IL-1β, IL-6 and TNF-α and anti-inflammatory cytokines such as IL-4 and IL-10 provide further insights into the mediators of cellular and systemic responses and have been linked to causal pathways related to atherosclerosis and thrombosis." (PMID 39767790, 2024). "Leptin, adiponectin, interleukin-6, and tumor necrosis factor are only a few cytokines and bioactive mediators released by adipose tissue, an active endocrine and paracrine organ that may affect blood flow and encourage atherosclerosis." (PMID 37168312, 2023). "Furthermore, FXa can affect the cytokine pathway by stimulating PAR activation on endothelial cells, which induces the overexpression of pro-inflammatory cytokines such as IL-1, IL-6 (by VSMCs), and IL-8 (by leukocytes), promoting atherosclerosis and thrombosis." (PMID 38003290, 2023). "Interleukin-6 inhibition has been tested in patients who may develop atherosclerosis." (PMID 37298597, 2023). "Vascular cell aging via IL-6 signaling is hypothesized to accelerate atherosclerosis." (PMID 37996879, 2023). "Atherosclerosis may be related to the increase in intracellular IL-6 levels." (PMID 37361203, 2023).
atherosclerosis (continued). "In agreement with our results, the Multi-Ethnic Study of Atherosclerosis showed that adherence to a dietary pattern containing a high amount of whole grains and a low amount of sodium was inversely associated with serum concentrations of CRP, IL-6, and homocysteine." (PMID 37496018, 2023). "Nucleotide oligomerization domain-like receptor family, pyrin domain containing 3 (NLRP3) and interleukin 6 (IL-6) are other inflammatory markers that have a demonstrated role in modulating the inflammatory processes involved in the development and progression of atherosclerosis." (PMID 37763676, 2023). "In atheroma, a CRP increase stimulates the induction of IL-6 by macrophages, suggesting that CRP may have a direct impact on IL-6 release; yet, an atherosclerosis model found that a combination of oxLDL along with the monomer and the pentamer decreases TNF-α and IL-6 production." (PMID 37873776, 2023). "First, macrophages often infiltrate abdominal adipose tissue, causing increased production of pro-inflammatory cytokines, such as interleukin-6 and tumor necrosis factor-α, which may induce oxidative stress and endothelial dysfunction, ultimately facilitating the development of atherosclerosis." (PMID 36320060, 2022). "Furthermore, through the modulation of inflammatory responses, with reduce expression of TNF-α, IL-6, IL-1, and IL-8 of monocytes, f TNF-α, IL-6, IL-1, and IL-8 of monocytes, Vitamina D may influence the pathophysiology of atherosclerosis." (PMID 35276762, 2022). "Additionally, Morin could reduce the TNF-α and IL-6 levels by inhibiting the PI3K/AKT/NF-κB pathway atherosclerosis which considered a chronic inflammatory disease." (PMID 35705830, 2022). "Taken together, our data demonstrate that Mettl14 plays a vital role in macrophage inflammation in atherosclerosis via the NF-κB/IL-6 signaling pathway, suggesting that Mettl14 may be a promising therapeutic target for the clinical treatment of atherosclerosis." (PMID 35598196, 2022). "IL-6 release from isolated atherosclerotic vascular segments over a 4-h incubation under organ culture conditions has been used as a reliable indicator of the presence of vascular inflammation due to atherosclerosis or to measure changes in inflammation as a response to treatments." (PMID 32748207, 2021). "In humans, a clinical trial proved that IL-6 is a major player in the inflammatory events leading to atherosclerosis and the blockade of this cytokine with specific inhibitors like tocilizumab may reduce cardiovascular risk, unfortunately with significant adverse reactions." (PMID 33925692, 2021). "Thus, the present study used the data of the Third China National Stroke Registry (CNSR-III) to investigate the combined effect of atherosclerosis vascular beds involvement numbers and IL-6 levels on the outcomes in patients with acute ischemic stroke (AIS) or transient ischemic attack (TIA)." (PMID 33927687, 2021). "Notably, Class IIa HDAC inhibitors attenuate inflammation in mouse and human macrophages, stabilize atherosclerotic plaques in mice and limit the expression of inflammatory factors IL‐1β and IL‐6 in monocytes from patients with atherosclerosis, a chronic arterial inflammatory condition." (PMID 34145738, 2021). "However, IL-6 has a two-sided role in the development of atherosclerosis." (PMID 34071276, 2021). "Thus, it could be hypothesized that the systemic proinflammatory status contributes to atherosclerosis in vitiligo patients and the crucial role might be played by the key cytokines in vitiligo pathogenesis, such as IL-1, IL-6, TNF-α, and possibly IL-17." (PMID 34445526, 2021). "Interestingly, IL-6 can exert both pro- and anti-inflammatory roles in atherosclerosis." (PMID 33812333, 2021).
atherosclerosis (continued). "However, inflammatory cytokines TNF-α, IL-1β, and IL-6 are important in atherosclerosis pathogenesis, as recently shown by the CANTOS trial, which found that specifically targeting inflammation (IL-1β inhibition) improves clinical outcomes in patients with a previous myocardial infarction." (PMID 32647892, 2021). "Thus, commonly used CHPs might suppress the production of IL-6 and TNF-α, the same proinflammatory cytokines active in the process of atherosclerosis, to reduce the risk of CAD." (PMID 32228568, 2020). "Given that atherosclerosis is an inflammatory disease promoted by specific cytokines, such as interleukin (IL)-1β, IL-6, and tumor necrosis factor (TNF)-α, we aimed at evaluating whether sex could affect the levels of these proatherogenic cytokines in a group of healthy adults." (PMID 32485823, 2020). "It has been shown that specific therapies targeting the pro/anti-inflammatory cytokines such as CCL2, TNFα, and IL-6 have suggested slowing in the progression of atherosclerosis in animal models and might improve cardiovascular outcomes in human subjects in large-scale phase III trials." (PMID 32821283, 2020). "The chronic inflammation is also a well-defined nontraditional CVD risk in the pathogenesis of atherosclerosis, where cytokines including IL-1, IL-6 and TNF-α could promote endothelial dysfunction, a key process in atherogenesis." (PMID 32665015, 2020). "Moreover, a positive feedback loop between IL6 and WNT5a exists in other diseases, which may indicate a similar mechanism in atherosclerosis." (PMID 33322009, 2020). "Furthermore, IL-6 is thought to play an important role in atherosclerosis in T2D." (PMID 32764458, 2020). "The common mechanisms shared in both are linked with atherosclerosis signaling and inflammatory response with at least the following target genes: Tnfrsf12a, Pla2g2f, Il1f9, Col1a1, Col1a2, and Col3a1 in brain, while Tnfrsf12a, SELP, SELE, IL6, and IL1A in myocardium." (PMID 29681850, 2018). "In addition, we observed that serum soluble VCAM-1 and P-selectin levels, which play a major role in the initiation of atherosclerosis, were reduced and the expressions of MCP-1 and IL-6 in aortas implicated in mediating the pathogenesis of atherosclerosis were decreased by BM treatment." (PMID 30400958, 2018). "Specifically, IL-6 is a cytokine derived from T lymphocytes, macrophages and adipocytes, and acts via its membrane-bound or soluble receptor, stimulating C-reactive protein, fibrinogen hepatic synthesis, and joint inflammation and accelerating atherosclerosis processes." (PMID 30223482, 2018). "Hence, by directly regulating IFN-γ and IL-6 secretion, sortilin could be a key regulator of inflammatory response increasing inflammatory component of atherosclerosis." (PMID 30666202, 2018). "Several previous reports indicate that IL-6 could accelerate atherosclerosis." (PMID 29312959, 2017). "In conclusion, an elevated IL-6 above 1 pg/mL in intermediate cardiovascular risk population submitted to coronary angiography may be highly predictive of CAD, being associated with the burden of atherosclerosis." (PMID 28878828, 2017). "In addition, PI-PLCγ1, activated by TLR4 stimulation with minimally oxidized LDL, induces ROS generation in macrophages, leading to the production of pro-inflammatory cytokines such as TNF-α, IL-1β and IL-6, all having central roles in the pathogenesis of atherosclerosis." (PMID 28661459, 2017).
atherosclerosis (continued). "While experimental studies reported the reduction of atherosclerosis upon MR blockade, other clinical studies revealed that aldosterone infusion raised circulating IL-6 levels in contrast to spironolactone, which blocked IL-6 accompanied with administration of angiotensin II." (PMID 27478508, 2016). "Nevertheless, resistin has primarily been shown to be relevant to inflammation-related diseases like atherosclerosis and arthritis and may have a role in the regulation of pro-inflammatory cytokines’ (IL-6 and TNF-α) expression in human peripheral blood mononuclear cells (PBMC) via NF-κB pathway." (PMID 27608037, 2016). "In addition, IL-6 and TNF-α can play a pivotal role in inflammation-associated disturbances in glucose and insulin metabolism, lipid homeostasis, endothelial dysfunction, and accelerated atherosclerosis." (PMID 27616738, 2016). "In addition to cholesterol and fat accumulation, macrophages serve as important regulators of inflammation in atherosclerosis development; while β-carotene induced changes in the inflammatory response in the Raw264.7 macrophage cell line and a reduction in IL-6 and TNF-α secretion to the medium." (PMID 25629601, 2015). "In addition, plasma pentosidine was strongly correlated with the markers of inflammation, such as CRP, fibrinogen and IL-6 and the levels of soluble vascular cellular adhesion molecule-1 (sVCAM-1) which play an important role in the development of atherosclerosis." (PMID 26645467, 2015). "Thus, anti-IL-6 therapies are still considered a double-edged sword in atherosclerosis management." (PMID 26578976, 2015). "Ceramide-loaded LDL has been shown to stimulate TNF-α and IL-6 production in cultured macrophages through NF-κB activation suggesting that ceramide-induced cytokine production in the circulation can target endothelial cells, which would exacerbate atherosclerosis through inflammatory mechanisms." (PMID 25993337, 2015). "Consequently, a variety of over-expressed cytokines such as tumour necrosis factor-α (TNF-α), interleukin-6 (IL-6) and IL-1β, may enter the systemic circulation and alter numerous pathways that potentiate the onset of atherosclerosis." (PMID 24874661, 2014). "We have observed that changes in the circulating concentration of IL-6 were nearly identical to the changes in plasma cholesterol concentration throughout the study, providing further evidence that atherosclerosis might induce systemic inflammatory responses directly." (PMID 25215291, 2014). "TNF-α and IL-6 have been reported to be significantly associated with the severity of subclinical atherosclerosis, independent of Framingham risk score in RA, and IL-6 was recently also documented to be very strongly and independently associated with surrogate markers of early atherogenesis in RA." (PMID 25514790, 2014). "High level of serum IL-6 may result in activation of inflammatory cells, dysfunction of vascular endothelial cells, and abnormal proliferation and migration of vascular smooth muscle cells, thereby accelerating the development of atherosclerosis." (PMID 25269085, 2014). "Traditional cardiovascular risk factors and inflammatory markers (hsCRP, IL-6, TNFα, adiponectin) were studied together with IMT (intima-media thickness), FMD (flow mediated dilation), and LVMi (left ventricle mass index) as surrogate markers of subclinical atherosclerosis." (PMID 23554546, 2013). "However, also other inflammatory mediators (IFN-γ, IL-1, IL-6) might play a role in the systemic inflammatory process of atherosclerosis in patients with DM, and their levels possibly also correlate with restenosis 6 months after stent implantation." (PMID 23305356, 2013). "Therefore in the early stages of atherosclerosis,inhibition of IL-6 and elevation of IL-17 by EEP might be one mechanism of its anti-AS effects." (PMID 23941539, 2013).
atherosclerosis (continued). "Our results indicate that the activation of CD14, TLR4, and TLR2 on monocytes and macrophages by a very early form of oxidized LDL induces the secretion of pro-inflammatory cytokines such as IL-1β and IL-6, which may contribute to or exacerbate inflammatory responses during atherosclerosis." (PMID 20946675, 2010). "At the same time the age-related estrogen deficiency may induce the increase of pro-inflammatory cytokines (IL1, IL6 and TNFα) that enhances the expression of adhesion molecules on leukocytes and endothelial cells favoring the progression of atherosclerosis plaques." (PMID 20948561, 2010). "Therefore reduced IL-6 release of T1D monocytes upon stimulation with HMW-APM may be beneficial in the development of atherosclerosis." (PMID 16939660, 2006). "Research into other inflammatory mediators, such as IL-6, TNF-α, and monocyte chemoattractant protein-1, with potential therapeutic options for preventing the rapid progression of atherosclerosis in NCVs is ongoing." (PMID 41517773, 2026). "Mercury also promotes vascular smooth muscle proliferation and endothelial inflammation via proinflammatory cytokines such as interleukin-6 and TNF-α, contributing to atherosclerosis, systemic hypertension, and cerebrovascular disease." (PMID 41323174, 2026). "In atherosclerosis and heart failure, endothelial dysfunction and plaque progression are driven by inflammatory cytokines (TNF-α, IL-6, CRP, etc.)and reactive oxygen species (ROS)." (PMID 41462689, 2025). "Increases SOD and GSH in serum in diseased mice.Suppresses the expression of IL-6, TNF-α, ICAM-1, VCAM-1 and NLRP3.Ameliorates atherosclerosis." (PMID 41300435, 2025). "For instance, mice with TET2 knockout bone marrow transplants showed accelerated atherosclerosis, activated through the NLRP-3/IL-1β inflammasome pathway and upstream IL-6 signaling." (PMID 40355940, 2025). "Inflammation is a key driver of atherosclerosis, with CRP, IL-6, and TNF-α serving as markers of disease activity." (PMID 40217801, 2025). "Chronic inflammation mediated by the Th17/IL-23/IL-17 axis promotes endothelial dysfunction and accelerates atherosclerosis through elevated levels of TNF-α, IL-17, and IL-6, which enhance vascular endothelial activation and plaque instability." (PMID 40777007, 2025). "Some cytokines can play both of these roles to a greater orlesser extent, for example: IL-6 and TGF-β, which creates prerequisitesfor further study into the pathogenesis of atherosclerosis." (PMID 40160593, 2025). "Compared to the blank group of mice, the levels of inflammatory factors IL-6 and TNF-α were significantly elevated in the ApoE−/− model group of mice with atherosclerosis." (PMID 40635740, 2025). "SGLT2 inhibitors inhibit atherosclerosis by normalizing the expression of inflammation-related genes such as TNF-α, IL-6, ICAM-1, MMP2, and MMP9." (PMID 40869372, 2025). "Pro-inflammatory mediators (IL6, TNF-α, and CRP) driven by periodontal disease are also known promoters of endothelial dysfunction, atherosclerosis, and destabilization of atherosclerotic plaque." (PMID 41011105, 2025). "IL-6 is a potent stimulator of CRP production, produced by vascular smooth muscle cells in reaction to atherosclerosis." (PMID 40933377, 2025). "Therefore, although the true effect might be different from 0, the observed effect sizes and confidence intervals suggest that any impact of IL‐6 signaling downregulation on cSVD outcomes would be smaller than the effects observed for atherosclerosis‐related end points." (PMID 41182006, 2025). "Abnormal overproduction of IL‐6, IL‐8, and TNF‐α are overlapped in almost diseases, prominently in degenerative (e.g., AD, osteoarthritis) and cardiovascular pathologies (e.g., atherosclerosis)." (PMID 41427020, 2025). "Hypomethylation of pro-inflammatory cytokines (IL-6, TNF-α) sustains inflammation, damages the vascular endothelium, and accelerates atherosclerosis." (PMID 41281553, 2025).